YAP1 (Yes1 associated transcriptional regulator)
Diseases named in the same sentence as YAP1 in open-access papers (continued):
Sharing a sentence is not in itself a finding about the gene and the disease.
cancer (continued). "We found that Yap1-mediated suppression of the UPR and clock support a shift in metabolism toward cancer cell-associated glycolysis and hyper-proliferation." (PMID 30382078, 2018). "Here, we identify the alteration of FAT1 as a recurrent event in human cancer acting in coordination with other YAP1 activating mechanisms." (PMID 29985391, 2018). "Intriguingly, Yap1 occupancy on apoptosis-related genes seems to be relatively conserved (r =~0.5) among different human cancer cell types." (PMID 30561326, 2018). "YAP1 overexpression and its contribution to cancer initiation and growth were reported in several cancer types." (PMID 30234141, 2018). "The IHC studies published so far underline the role of YAP1 in the course of several types of cancers of the alimentary tract and demonstrate the correlation between higher expression of YAP1 protein, cancer development, and poor patients' prognosis." (PMID 29850494, 2018). "As the key downstream mediator of Hippo pathway, YAP1 is activated in multiple cancer types and functions as a driver oncogene, even bypassing oncogenic RAS signaling." (PMID 29367737, 2018). "Herein, we identified cancers in which Hippo pathway affects OS; these cancers should be candidates for YAP1 inhibitors development and testing." (PMID 30006603, 2018). "The Yap1 protein is known to be oncogenic as it promotes growth while inhibiting apoptosis, and is amplified or overexpressed in a number of cancer types." (PMID 30322398, 2018). "Immunostaining data clearly showed that YAP1-depleted cancer cells exhibit longer protrusions on HUVEC layers." (PMID 30504771, 2018). "This can explain differences in the expression of YAP1 and pYAP1 in the cytoplasms and nuclei of carcinoma cells." (PMID 28782275, 2018). "TAZ (WWTR1 is the gene) and YAP (YAP1 is the gene) are developmentally important transcriptional coactivators that have emerged as central oncoproteins in a number of carcinomas including breast, colon, liver, lung, pancreas, and thyroid cancers." (PMID 30167083, 2018). "Here, we showed that platelets interact with cancer cells in a low-attachment environment and induced a YAP1-dependent transcriptional program which enhanced cancer cell survival and metastasis in vitro and in vivo." (PMID 28827520, 2017). "YAP1, the main downstream regulator of the Hippo pathway, is highly expressed in cancer cells and involved in cell proliferation and tumorigenesis." (PMID 29179447, 2017). "This further indicates that platelets induce an active dephosphorylation of YAP1 in cancer cells, which in turn activates YAP1 signaling allowing survival under low-attachment conditions." (PMID 28827520, 2017). "The downstream transcriptional activator of the Hippo pathway is YAP1, which is described as an oncogenic factor often activated in cancer." (PMID 29179447, 2017). "Platelet interaction with cancer cells led to activation of RhoA and YAP1 dephosphorylation via the PP1-MYPT1 phosphatase which induced nuclear localization of the protein." (PMID 28827520, 2017). "Constitutively active forms of YAP1 have been shown to stimulate cancer cell migration and invasion." (PMID 28098159, 2017). "In the present study, we demonstrate that YAP1 and ∆Np63α are important sulforaphane cancer prevention targets." (PMID 29088716, 2017). "This study is the first to demonstrate that pharmacological inhibition of LSD1 in OSCC and other cancer types attenuates the YAP1 oncogenic pathway." (PMID 29088714, 2017). "YAP1, an effector of Hippo signaling, has emerged as a crucial player in the proliferation and survival of cancer cells." (PMID 29163769, 2017). "We next looked at the relative expression of INSM1 and YAP1 among all cancer cell lines in the CCLE." (PMID 29088741, 2017). "Because amplification is one common activation mechanism of YAP1, we first examined copy number alteration of YAP1 in 26 cancers by using genome copy number data from TCGA." (PMID 29340043, 2017).
cancer (continued). "A meta-analysis on YAP1 expression in various cancers and its prognostic implication reported that upregulation or nuclear expression of YAP1 indicated a worse disease-free survival time and a reduction in the overall survival time (OS)." (PMID 28645247, 2017). "YAP1 is a transcriptional co-activator in Hippo signaling and has received extensive attention for its remarkable biological properties in cancers." (PMID 29113304, 2017). "When co-cultured with YAP1-silenced DLD-1 cancer cells, THP-1 monocytes differentiated into macrophages expressing a significantly reduced M2 marker." (PMID 28241877, 2017). "Although activation of YAP1 has been reported in many cancers, its relative activity across all cancer types has not been systematically examined." (PMID 29340043, 2017). "Here, we demonstrate that frictional force characteristic of flow in the lymphatics stimulates YAP1 to drive cancer cell migration; whereas intensities of fluid wall shear stress (WSS) typical of venous or arterial flow inhibit taxis." (PMID 28098159, 2017). "Since YA subtype is poor prognostic, it would be also interested to see if YAP1-mediated low immune activity contributes to aggressiveness of cancer cells in YA subtype in future study." (PMID 29340043, 2017). "Our study provides several lines of evidence for an expanded role for YAP1 in lung SP cells or cancer stem-like cells." (PMID 27911857, 2017). "To obtain direct evidence supporting this concept, we performed RNAi-mediated knockdown experiments in HEYA8 and OVCAR8 cancer cells using two independent siRNAs that reduced YAP1 at RNA and protein levels." (PMID 28827520, 2017). "Here, we demonstrate that WSS characteristic of flow within the lymphatic vasculature regulates YAP1/TAZ to modify cancer cell motility using a soft-polymer microfluidics system engineered for the study of mechanobiology." (PMID 28098159, 2017). "Hyperactivation of YAP1 is wide-spread in cancers and YAP1 expression and nuclear localization strongly correlate with poor patient outcome and progression of cancer." (PMID 29228705, 2017). "YAP1 was rapidly activated by low-level WSS typical of the lymphatic vasculature to drive cancer cell motility." (PMID 28098159, 2017). "We have identified the dual function of YAP1 where its suppression not only inhibited tumorigenesis but also prevented the generation of cancer stem-like cells and M2 TAM polarization." (PMID 28241877, 2017). "YAP1/TAZ have various roles in the regulation of homeostasis, and their dysregulation is associated with tumorigenesis and cancer progression." (PMID 29212185, 2017). "Conversely, the same genes were significantly deregulated by knocking down YAP1 with two individual siRNAs, indicating that platelets induce a YAP1-dependent gene signature in cancer cells." (PMID 28827520, 2017). "In tumorigenesis, YAP1 has been known as an oncogene, due to of its function in promoting cancer cell survival, proliferation, invasion, and migration in several types of malignancies." (PMID 28645247, 2017). "Dysregulation of the Hippo pathway leading to abnormal activity of YAP1/TAZ (e.g., a high protein level of YAP1/TAZ and/or low phosphorylation level by LATS) has been associated with cancer development." (PMID 27911857, 2017). "Taken together, our results suggest that a network of YAP1-dependent genes sensitive to WSS contribute to invasive cancer cell behaviour in the lymphatics." (PMID 28098159, 2017). "YAP1 also reportedly contributes to promoting resistance to anticancer drugs in different cancers like ovarian cancer and hepatocellular carcinoma cells." (PMID 27911857, 2017). "With the widespread involvement of YAP1 activation in different cancers, drugs blocking YAP1 activity through different mechanisms can be promising cancer therapeutics." (PMID 29163769, 2017).
cancer (continued). "Yes-associated protein 1 (YAP1), a downstream molecule of the Hippo signaling pathway, has been identified as an oncogene involved in cancer-promoting processes such as cell proliferation and metastasis." (PMID 27901498, 2017). "This work suggests YAP1 and TAZ play distinct roles in the response to mechanical cues and identifies the ROCK–LIMK–YAP1 signalling axis as a central component of the mechanosensory transduction machinery that promotes flow-induced motility of cancer cells." (PMID 28098159, 2017). "Because YAP1 holds potential for cancer therapy, the mechanism by which the YAP1 inhibitor verteporfin exerts its action has also been studied." (PMID 27911857, 2017). "TAZ (a paralog of Yap1) as a downstream effector of the Hippo pathway is highly expressed in many human cancers." (PMID 26695440, 2016). "Culminating evidence suggest that YAP1 is involved in the modulation of cancer cell proliferation, self-renewal of cancer stem cells and initiation of migration and metastasis." (PMID 26716514, 2016). "In the case of the MST/Hippo pathway, the bulk of studies within the cancer setting have assigned YAP1/2 and TAZ to behave as oncogenes." (PMID 27322327, 2016). "We showed that YAP1, a key oncogene in a subset of ovarian and other cancers, is a direct downstream target of miR-509-3p." (PMID 27036018, 2016). "YAP1 is a transcription factor that has several characteristics that make it a target of interest in cancer biology." (PMID 28286866, 2016). "Collectively, expression levels of BRG1 and YAP1 target genes are well related to cancer severity and prognosis of HCC patients." (PMID 27905400, 2016). "Collectively, our findings provide significant new insights for a broad range of research efforts aimed at decoding and eventually manipulating YAP1-driven biology with the aim of improving cancer treatment and regenerative medicine." (PMID 25601544, 2015). "Since YAP1 is mainly involved in regulating the transcriptional outcome to govern cell proliferation and survival, it can be hijacked by cancer cells to facilitate their own growth, including induction of cancer stem cells and metastatic colonization." (PMID 25473897, 2015). "Results of overall and subgroup analyses for effects of YAP1 expression on overall and disease-free survival in cancer." (PMID 26263504, 2015). "Further, YAP1 interaction with transcription factors such as TEAD1-4 in the nucleus can promote cancer cell proliferation, anchorage-independent growth, EMT and metastasis." (PMID 25473897, 2015). "Elevated activity of YAP1, a transcriptional coactivator and well-established oncogene has been reported to occur in human cancers." (PMID 26295846, 2015). "YAP-1 is frequently overexpressed in many types of cancers and mediates constitutive and acquired treatment resistance in EAC cells." (PMID 26317542, 2015). "Aside from presenting a global view of YAP1 and TEAD1 binding in a cancer context, our study also provides novel mechanistic insights into YAP1 transcriptional co-activation of TEAD TFs." (PMID 26295846, 2015). "The identified distal regions enabled us to largely expand the set of YAP1 target genes, which we foresee to be a valuable source for functional studies and which we show to have predictive power to identify YAP1-activated cancers." (PMID 26295846, 2015). "In a separate study, β-catenin-active cancers were reported to be dependent on a signaling pathway involving the transcriptional regulator YAP1 and the transcription factor TBX5, both of which form a complex with β-catenin." (PMID 26134786, 2015). "In the present study, by using eligible relevant literatures, the first meta-analysis was conducted to achieve a precise evaluation of YAP1 prognostic value in various cancers." (PMID 26263504, 2015). "Further, YAP1 overexpression in multiple cancer cell lines can promote proliferation, inhibit apoptosis and enhances in vitro invasive and metastatic capacity." (PMID 25473897, 2015).
cancer (continued). "YAP1/β-catenin promote cancer cell proliferation and tumorigenesis via TBX5 but also promote overgrowth of the heart through binding to TEAD." (PMID 26549256, 2015). "Subgroup analysis showed that both positive nuclear YAP1 (HR = 1.390, 95% CI: 0.810–2.400, p = 0.729) and up-regulation overall YAP1 (HR = 2.237, 95% CI: 1.548–3.232, p <0.001) had poorer OS for patients with malignancies." (PMID 26263504, 2015). "YAP1 re-expression in rescuing the suppressive phenotypes of cancer cells by ectopic expression of miR-15a and miR-16-1 was investigated." (PMID 25743273, 2015). "In this study we demonstrate that YAP1 effectively supports multiple transformed properties in 11q22-amplified cancer cell lines." (PMID 24810989, 2014). "In conclusion, our results demonstrate that in the YAP1-amplified cancer cell lines under study the YAP1 gene effectively sustains multiple transformed traits, indicating that YAP1 is a direct oncogenic target of the 11q22 amplicons." (PMID 24810989, 2014). "Recently, YAP1 has been suggested to be part of a complex required for survival of β-catenin driven cancers including CRC." (PMID 24892549, 2014). "Among these target genes, 505 are down-regulated and 202 are up-regulated upon YAP1 silencing (Chi-square p-value < 0.0001), thus suggesting that YAP1 mainly acts as a transcriptional co-activator in the cancer cell lines under study." (PMID 24810989, 2014). "In the present work we corroborate that YAP1 plays an important role in the tumorigenic phenotype of 11q22-amplified cancer cell lines, as it effectively supports multiple transformed properties." (PMID 24810989, 2014). "On the contrary, YAP1 was also described to function as an oncogene by promoting increased organ size and cancer development." (PMID 24810989, 2014). "SOX9, Shh and YAP1 were overexpressed in many cancer cell lines compared to BE cell lines (CP-A and CP-C) indicating the activation of stem cell signaling in EC cells." (PMID 24859412, 2014). "YAP, a transcriptional co-activator amplifier, is a pivotal effector of the Hippo pathway in mouse and human cancers; YAP1 and YAP2 are potent oncogenic drivers and independent prognostic risk factors for HCC." (PMID 24694742, 2014). "Our results provide definitive evidence that endogenous YAP1 expression has oncogenic properties in cancer cells carrying YAP1 gene amplification." (PMID 24810989, 2014). "Preliminary experiments were performed in order to verify YAP1 amplification in these established cancer cell lines and to evaluate the occurrence of YAP1 protein overexpression." (PMID 24810989, 2014). "YAP1 silencing induced a strong and significant reduction in the number and size of colonies counted in all 11q22-amplified cancer cell lines analyzed, compared to the control cells." (PMID 24810989, 2014). "In pancreatic cell lines, YAP1 protein expression and localization is regulated by cell density, but such regulation seemed to be diminished significantly in cancer cells compared to that in normal ductal epithelial cells." (PMID 22396793, 2012). "This indicates that relatively more YAP1 remain activated (unphosphorylated) in the cancer cell lines than in the immortalized normal HPDE6 cell line when cells become confluent." (PMID 22396793, 2012). "In the cancer cells, on the other hand, p-YAP1 is present at low cell densities and increases as the cells become more confluent." (PMID 22396793, 2012). "It has been reported that YAP1 is a transcriptional regulator and acts as a oncoprotein in various carcinomas." (PMID 22185343, 2011). "This enhances YAP1 transcriptional activity, promoting cancer cell motility." (PMID 41256331, 2025). "Notably, elevated YAP1 expression has been positively correlated with increased MDSC infiltration across multiple cancer types." (PMID 41028521, 2025). "Given the frequent upregulation of YAP1 and CK2α in a variety of human cancers, we next investigated whether CK2α regulated YAP1 in other cancer types." (PMID 39827153, 2025).
cancer (continued). "DUB3 depletion in A2780 and SKOV3 cells significantly decreased cell proliferation and sensitized cancer cells to cisplatin in vitro and in vivo, whereas reconstitution of YAP1 in DUB3-depleted cells could markedly rescued these phenotypical changes." (PMID 39827153, 2025). "Besides, YAP1-mediated increase of cancer stem cell population also contributed to the recurrence of GC after first-line treatment." (PMID 40604818, 2025). "YAP1 is another major signal molecule for regulating organ growth and cancer progression." (PMID 39582289, 2025). "However, its clinical potential for treating YAP1‐TEAD‐driven cancers is constrained by off‐target effects." (PMID 39968498, 2025). "However, frequent dysregulations of YAP1 contributes to cancer stemness, chemoresistance and increased cancer‐related mortality, making YAP1 a promising drug target." (PMID 39968498, 2025). "YAP1 plays vital roles in the resistance to multidrug in various cancers." (PMID 41184230, 2025). "Also, miR-34a-5p suppresses the signaling pathways that are key regulators in metabolic function related to the growth of cancer including Hippo-YAP1/TAZ, TRIM44, and FLSs-RA." (PMID 40061926, 2025). "Additionally, M2d cells highly expressed Cd274 (which encodes programmed death–ligand 1 [PD-L1]), but Cd274 expression was reduced when Yap1 was silenced in cancer cells." (PMID 39946200, 2025). "In addition, COX-2-mediated hypoxia in the TME, along with its positive interactions with YAP1 and anti-apoptotic factors, collectively contributes to cancer cell resistance to chemotherapeutic drugs." (PMID 41259576, 2025). "In addition, lncRNA ASAP1 intronic transcript 1 (ASAP1-IT1) sponges miR-509-3p to derepress yes-associated protein 1 (YAP1), thus activating the Hippo pathway effector and enhancing cancer stemness in NSCLC." (PMID 41409273, 2025). "Sponges miR-509-3p to derepress YAP1, enhancing cancer stemness." (PMID 41409273, 2025). "In addition to subtype markers (ASCL1, NEUROD1, POU2F3, and YAP1), the expression of nine cancer-specific proteins was evaluated." (PMID 40107154, 2025). "In cancer, post-translational regulation of YAP1 adds further complexity." (PMID 40977060, 2025). "In general, data show that μg, by inhibiting mechanical signals, reducing NF-κB phosphorylation, inhibiting FAK/RhoA, and weakening the nuclear localization of factors such as YAP1, leads to a reduction in the invasion, migration, and potential metastasis of cancer cells." (PMID 40940834, 2025). "Notably, YAP1 is hyperactivated in many cancers, where it sustains stem cell properties and enhances cancer stem cell traits, contributing to therapeutic resistance, recurrence, and metastasis." (PMID 40784457, 2025). "FSS activates the RhoA/YAP1 axis to induce promigratory autophagy in cancer cells." (PMID 40977060, 2025). "The distribution of reads obtained via ChIP-Seq was strongly associated with the Hippo and Notch signaling pathways in cancer cells or tumors, whereas the PI3K-AKT signaling pathway in primary human TH1 cells were shown as the robust tracks of the YAP1, Notch1 or AKT1 gene promoter region." (PMID 40430053, 2025). "Moreover, we reveal that DUB3 as a bona fide deubiquitinase of YAP1, which functionally links CK2 and YAP1 stability in a variety of human cancers." (PMID 39827153, 2025). "And more druggable upstream regulators of YAP1 in cancers such as HCC are largely unknown and require further investigation." (PMID 40307228, 2025). "By providing a holistic view of YAP1's multifunctional roles, this review seeks to bridge mechanistic insights with therapeutic potential, offering valuable perspectives for future research and cancer treatment strategies." (PMID 40977060, 2025). "Collectively, these findings suggest that PP1γ may regulate YAP1 dephosphorylation and promote the expression of cancer stem cell markers SOX2 and NANOG, thereby enhancing the tumorigenic potential of ESCC cells." (PMID 40626009, 2025).